EPO (erythropoietin)
Diseases named in the same sentence as EPO in open-access papers (continued):
Sharing a sentence is not in itself a finding about the gene and the disease.
thalassemia (18 papers, 2015 to 2024). An inherited blood disorder characterized by a decreased synthesis of one of the polypeptide chains that form hemoglobin. "Elevated ERFE expression is associated with increased erythropoietin and hepcidin suppression in mice models with thalassemia intermediate during stress erythropoiesis." (PMID 35052868, 2022). "For clinical translation, physicians should evaluate BMD and serum levels of erythropoietin in thalassemia patients with CKD before initiating treatment since the reduced erythropoietin might already protect against bone loss in these patients." (PMID 32385316, 2020). "Chronic anemia in thalassemia markedly stimulates the erythropoietin production, however, elevated erythropoiesis is ineffective because erythroid progenitor precursors fail to mature, and die in the process of becoming erythrocytes." (PMID 35622784, 2022). "Chronic anemia in thalassemia markedly stimulates the production of erythropoietin up to 20–30 times normal level with consequent massive medullar cell proliferation." (PMID 32385316, 2020). "Other marked changes are a large increase of NTBI and EPO, and a severe reduction of hepcidin, which are also characteristic of the thalassemia major phenotype." (PMID 30608934, 2019). "The trends in other variables, such as increased NTBI, Tf saturation, and EPO and lower hepcidin are also in good agreement with experimental observations in a thalassemia mouse model." (PMID 30608934, 2019). "In SCD and thalassemia bone abnormalities have been attributed mainly to marrow expansion, although a linear correlation between circulating EPO levels and degree of bone demineralization in patients with identical diseases lacked." (PMID 30971944, 2019). "FGF23 mRNA expression in bone and BM of thalassemia intermedia mice were elevated, reaching expression levels of endogenous EPO-overexpressing, polycythemic mice." (PMID 30971944, 2019). "In this case, EPO stimulates the bone marrow to produce more red blood cells to compensate for the low hemoglobin that accompanies thalassemia." (PMID 30064480, 2018). "A severe anemic condition in thalassemia activates erythropoietin (EPO) induced erythroid hyperplasia." (PMID 28303002, 2017). "In individuals with thalassemia major and intermedia, liver hepcidin mRNA expression is inversely associated with soluble transferrin receptor (sTfR) and erythropoietin (EPO), but not with iron storage." (PMID 35052868, 2022). "BKO mice had high circulating level of erythropoietin similar to thalassemia patients." (PMID 32385316, 2020). "Low averaged steady state hemoglobin levels were associated with high EPO, increased reticulocyte %, lower SpO2, the absence of co-inheritance of α-thalassaemia deletions, and lower levels of fetal hemoglobin." (PMID 30056060, 2018). "Increased serum erythropoietin was reported in thalassemia patients; which thereby might account for the increased nitrite blood levels." (PMID 30235277, 2018). "In addition, treatments with EPO and certain drugs, such as hydroxyurea, hydroxybutyrate and DFP, will increase the production of fetal Hb and lead to the subsequent switching to adult Hb in thalassemia patients." (PMID 36620219, 2022). "Moreover, an efficient production of β-globin by β°39-globin mRNA was reported in erythroid precursor cells isolated from six homozygous β°39-thalassemia patients and treated with erythropoietin (EPO) with or without G418." (PMID 31972957, 2020).
endothelial dysfunction (17 papers, 2008 to 2025). In vascular diseases, endothelial dysfunction is a systemic pathological state of the endothelium (the inner lining of blood vessels) and can be broadly defined as an imbalance between vasodilating and vasoconstricting substances produced by (or acting on) the endothelium. "Indoxyl sulfate has also been negatively associated with EPO expression and positively associated with EPO resistance and endothelial dysfunction." (PMID 38787184, 2024). "Although co-treatment with ESC and EPO showed comparable antioxidant, anti-inflammatory and anti-apoptotic activities, and improvement in endothelial dysfunction, yet the underlying mechanisms were different." (PMID 35422072, 2022). "EPO‐induced endothelial dysfunction was significantly associated with carotid stiffness and history of cardiovascular events." (PMID 23584809, 2013). "EPO stimulation of vascular endothelium in culture and animal models promotes eNOS expression and NO production, and is associated with prevention or improvement of endothelial dysfunction." (PMID 36895793, 2023). "The studies summarized suggest that EPO protects against NOXs-generated ROS-mediated endothelial dysfunction and vascular damage." (PMID 35741081, 2022). "EPO was also found to protect against vascular and endothelial dysfunction from NOX-mediated oxidative stress." (PMID 35741081, 2022). "They attributed these favourable effects of EPO to the induction of new capillary formation and correction of endothelial dysfunction." (PMID 27561278, 2016). "Others have suggested that endothelial dysfunction and microvascular damage in the renal tubulointerstitium which were thought to be the pathogenesis of albuminuria, can lead to the impairment of EPO production and release." (PMID 26430892, 2015). "We tested the effect of tempol, an antioxidant superoxide dismutase mimetic, on endothelial dysfunction induced by EPO." (PMID 23584809, 2013). "Vascular cells, such as endothelial and smooth muscle cells, and macrophages express EPO receptors, and our previous study showed that EPO inhibited endothelial dysfunction and macrophage infiltration by nitric oxide production from endothelial cells via the PI3K/Akt pathway." (PMID 40943240, 2025). "EPO‐induced endothelial dysfunction could contribute to deleterious effects of EPO described in large interventional trials." (PMID 23584809, 2013). "In addition, endothelial dysfunction observed in the presence of EPO was partially prevented by ABT‐627, an ETAR antagonist." (PMID 23584809, 2013). "Its pathophysiology extends beyond reduced erythropoietin (EPO) synthesis and includes chronic inflammation, iron dysregulation, and endothelial dysfunction." (PMID 40648948, 2025).
leukemia (17 papers, 2008 to 2025). A malignant (clonal) hematologic disorder, involving hematopoietic stem cells and characterized by the presence of primitive or atypical myeloid or lymphoid cells in the bone marrow and the blood. "We observed a low rate of disease progression to AML or other leukaemias, in accordance with other studies evaluating the use of darbepoetin alfa or erythropoietin alfa in low-risk MDS patients." (PMID 18540943, 2008). "The direct effect of EPO on MPPs we described here could be one of the factors underlying the development of adverse side effects and comorbidities during long-term EPO use in the clinics and associations of high EPO levels with leukemias." (PMID 35166672, 2022). "Finally the biological activity of the plant-derived rhEPOFc variants was analysed using an erythropoietin-dependent human leukemia cell line, UT-7." (PMID 23372778, 2013). "When subjected to s-μg using a rotary culture, an experiment on the UT-7/EPO leukemia cell line showed a noticeable decrease in surface localization, protein content, and mRNA expression of the erythropoietin receptor (EPOR)." (PMID 38255998, 2024). "Erythropoietin (EPO) suppresses drug-induced apoptosis in EPO-receptor-positive leukemia cells and allows cells to persist after drug treatment by promoting cellular senescence." (PMID 37543610, 2023). "Here we demonstrate that EPO protects DA3/EPOR leukemia cells from drug-induced cell death by promoting and maintaining senescence." (PMID 37543610, 2023). "Here we examine the ability of EPO to protect DA3/EPOR murine leukemia cells from stress-induced apoptosis." (PMID 30622244, 2019). "It has been shown that erythropoietin protects leukemia cells from imatinib-induced killing by promoting erythroid differentiation." (PMID 28978042, 2017). "We surveyed EPO and EPOR expression in nine NSCLC cell lines with normal bronchial epithelial cells HBEC-3KT and EPO-dependent leukemia cells UT-7 included as controls." (PMID 29137269, 2017). "Growth of the human leukemia cell line UT-7 is strictly correlated to the concentration of EPO in the culture medium." (PMID 23325672, 2013). "In the first stage of leukemia, the envelope protein encoded by SFFV interacts with and activates the erythropoietin (Epo) receptor and the receptor tyrosine kinase sf-Stk in erythroid cells, causing their Epo-independent proliferation, differentiation and survival." (PMID 21994618, 2010). "Recently, EPO has also been suggested to act on hematopoietic stem and progenitor cells (HSPCs), but the nature of EPO’s effect on HSPC fate remains unresolved despite potential adverse side effects during long-term EPO usage in the clinics and associations of high EPO levels with leukemias." (PMID 35166672, 2022). "In particular, EP was found to inhibit the proliferation of many leukemia cell lines, with IC50 values ranging from 0.56 to 21 μg/mL even in the presence of cytokines, such as granulocyte colony-stimulating factor (G-CSF), erythropoietin or Tpo." (PMID 35140693, 2021). "EPO and EPOR were found in 24 different types of malignant tumors, including leukemia." (PMID 37663284, 2023).
myocardial ischemia (17 papers, 2012 to 2023). A disorder of cardiac function caused by insufficient blood flow to the muscle tissue of the heart. "Other possible mechanisms include the inhibition of sodium-hydrogen exchange, increase in erythropoietin levels, and reduction in myocardial ischemia or reperfusion injury." (PMID 34650428, 2021). "It has been demonstrated that Erythropoietin reduces myocardial ischemia-reperfusion injury, and the activation of PI3K/Akt signaling pathway and down-regulation of GSK-3β gene expression were required." (PMID 30237226, 2019). "Treatment with erythropoietin (EPO) during cardiac ischemia decreases the chance of myocardial apoptosis." (PMID 30510626, 2018). "In transgenic knockout mice with EPOR2 being expressed only in bone marrow and on vascular endothelial cells, EPO was still protective in a model of traumatic brain injury as well as in cardiac ischemia." (PMID 29127105, 2017). "Dose regimes in cardiac ischemia-reperfusion worked also primarily with high doses of 2500–5000 IU/kg of body weight erythropoietin intraperitoneal or intravenous and most regimes included a dose given even before ischemia was induced." (PMID 28109258, 2017). "The concept of an endothelial-specific EPO pathway was further supported by findings that when eNOS knockout mice were used in cardiac ischemia model, reduced protective effects of EPO were observed." (PMID 29127105, 2017). "The growing literature on erythropoietin effect on cardiac ischemia led us to question its effect on cardiotoxicity due to the carbon monoxide poisoning." (PMID 24250553, 2012). "We compared the impact of the interleukin-1 receptor antagonist Anakinra and erythropoietin on myocardial ischemia/reperfusion injury." (PMID 22649318, 2012). "In this context, we also decided to apply Anakinra and erythropoietin via a central venous access site in order to quickly achieve systemic drug circulation despite circulatory depression during cardiac ischemia." (PMID 22649318, 2012). "For the first time, results of our study have indicated the effect of EPO on reducing cardiac ischemia following CO poisoning." (PMID 24250553, 2012). "In context with myocardial ischemia, erythropoietin has been shown to decrease cardiomyocyte apoptosis in different experimental settings." (PMID 22649318, 2012). "Hence, eNOS activation and endothelial response is suggested to be sufficient for the observed EPO activity in cardiac ischemia/reperfusion injury." (PMID 24918289, 2014). "Other in-vivo studies of cardiac ischemia in rat model indicated that EPO could have acute cardioprotective effect at 5000 IU/Kg with reduction in cardiomyocyte loss, infarct size and apoptosis, and also normalization of hemodynamic function." (PMID 24250553, 2012). "Increasing evidence suggests that EPO ameliorates cardiac remodeling and improves cardiac function by exerting anti-fibrotic effects in the myocardial ischemia model, but the underlying mechanism has not been totally elucidated." (PMID 22954171, 2012). "Results of these studies show that hypoxia is involved in cerebral edema, tumorigenesis, myocardial ischemia and some genes including Endothelin 1 (EDN1), Erythropoietin (EPO) and Aldosterone synthase (CYP11B2) are reported as the key genes of hypoxia adaptation." (PMID 37735456, 2023). "While experimental evidence for a protective role of erythropoietin in myocardial ischemia has been promising, clinical trials so far have not been able to proof this hypothesis." (PMID 22649318, 2012).
vitamin D deficiency (17 papers, 2014 to 2025). A nutritional condition produced by a deficiency of VITAMIN D in the diet, insufficient production of vitamin D in the skin, inadequate absorption of vitamin D from the diet, or abnormal conversion of vitamin D to its bioactive metabolites. "OS, higher ferritin and CRP levels, lower hemoglobin, hematocrit and prealbumin levels, and vitamin D deficiency represent significant risk factors for EPO resistance development in HD patients." (PMID 35464768, 2022). "The supplementation of vitamin D deficiency with ergocalciferol is a simple and cost effective measure but we were unable to demonstrate its benefit on EPO requirement and hospitalization rate in hemodialysis patients." (PMID 27717322, 2016). "According to Li and associates vitamin D deficiency results in dysregulation of innate immunity and inflammation which is affecting iron metabolism and contributes to erythropoietin resistance." (PMID 24992690, 2014). "The progressive loss of glomerular filtration rate (GFR) induces multiple comorbidities, such as fluid retention, electrolyte imbalance, vitamin D deficiency, renal anemia mediated through insufficient erythropoietin (EPO) production by the kidney, and uremic toxin accumulation." (PMID 34122041, 2021). "Studies have shown that vitamin D can reduce the level of erythropoietin, so vitamin D deficiency may increase the occurrence of neonatal jaundice." (PMID 34043645, 2021). "Other contributing factors include erythropoietin resistance, perturbations in the FGF23 pathway, and vitamin D deficiency." (PMID 35795334, 2022). "Additionally, impaired erythropoietin (EPO) synthesis and vitamin D deficiency can cause renal anemia and renal osteodystrophy." (PMID 41262737, 2025). "Recent reports, however, suggest that EPO resistance to high PTH levels is probably related to vitamin D deficiency, whose levels were not assessed in previous studies." (PMID 25781618, 2015).
schizophrenia (16 papers, 2005 to 2024). A major psychotic disorder characterized by abnormalities in the perception or expression of reality. "This is somewhat reminiscent of the findings in schizophrenia where EPO halted the loss of gray matter in the cortex." (PMID 34552490, 2021). "In schizophrenia and affective disorders, we even detected in independent trials reduction of grey matter loss upon EPO." (PMID 32546125, 2020). "Suboptimal pre-dialysis renal care, less access to nephrologists’ visits, and fewer chances for EPO prescription in patients with schizophrenia coincided with their higher risk for hospital admission and death after dialysis." (PMID 26469976, 2015). "We wondered whether EPO deficiency mediated schizophrenia‐related synaptic dysfunction." (PMID 39467064, 2024). "Dialysis patients with schizophrenia received inferior pre-dialysis renal care as evidenced by less access to nephrologist visits and less EPO prescription." (PMID 26469976, 2015). "In a recent double-blind, placebo-controlled, proof-of-concept study in chronic schizophrenic patients, we showed that EPO improved schizophrenia-relevant cognitive performance independently of its hematopoietic effects." (PMID 18782446, 2008). "In fact, EPO turned out to be the first compound to exert a selective and lasting beneficial effect on cognition in schizophrenia." (PMID 18782446, 2008). "However, no head-to-head studies have compared the neurocognitive effects of metformin with sulforaphane or erythropoietin in adults with schizophrenia." (PMID 39902241, 2024). "Interestingly, EPO appears to be the only drug capable of delaying the progressive thinning of the cortex that occurs in schizophrenia, correlating with an improvement in attention and memory." (PMID 34552490, 2021). "Patients in the dialysis-schizophrenia subgroup seemed to have lower incomes, higher CCI scores, lower chances of seeing nephrologists or receiving EPO prescription before dialysis, and were more likely to receive HD as the dialysis modality." (PMID 26469976, 2015). "Patients with schizophrenia in the late stage of CKD received suboptimal pre-dialysis renal care, including less access to nephrologists and fewer chances to receive EPO prescription." (PMID 26469976, 2015). "Patients with schizophrenia at the pre-ESRD stage received suboptimal pre-dialysis renal care; for example, they were less likely to visit nephrologists (OR = 0.6; 95% CI, 0.4–0.8) and received fewer erythropoietin prescriptions (OR = 0.7; 95% CI, 0.6–0.9)." (PMID 26469976, 2015).
Encephalopathy (15 papers, 2012 to 2025). Encephalopathy is a term that means brain disease, damage, or malfunction. "There is a case report of using EPO in the treatment of encephalopathy associated with CO poisoning." (PMID 23493953, 2012). "An interesting finding is the elevated levels of EPO in neonates with moderate and severe encephalopathy, particularly in the subgroup with severe encephalopathy (hypothesis A)." (PMID 40149963, 2025). "This study is a preplanned secondary analysis of prospectively collected data from infants enrolled in the High-Dose Erythropoietin for Asphyxia and Encephalopathy (HEAL) Trial, which tested the efficacy of erythropoietin as an adjunctive neuroprotective therapy to therapeutic hypothermia." (PMID 37418263, 2023). "Additionally, EPO levels were correlated with CPCs levels of the same or the following days, an observation found only in the group of prematures with encephalopathy." (PMID 37292373, 2023). "However, the HEAL randomised controlled trial of high dose EPO for perinatal asphyxia and encephalopathy in term infants did not lower risk of death or neurodevelopmental impairment and was associated with a higher risk of adverse events." (PMID 40661891, 2025). "Our results indicate that specific patterns of CPC mobilization, in conjunction with the levels of EPO, IGF-1, and SDF-1, are strongly associated with the severity of encephalopathy and may offer valuable information regarding pathophysiological pathways and outcome." (PMID 40149963, 2025). "Although there is evidence to suggest that EPO has neuroprotective properties, the recently published results of the High-Dose Erythropoietin for Asphyxia and Encephalopathy (HEAL) trial (NCT02811263) did not demonstrate a neuroprotective effect." (PMID 39237728, 2024). "At this point, as it has previously been stressed out there are no preclinical data showing the neuroprotective effects of EPO in a model of encephalopathy of prematurity, limiting the understanding of the best paradigm to deliver neuroprotection in this population." (PMID 33043002, 2020).